FOXP3 (forkhead box P3)
Diseases named in the same sentence as FOXP3 in open-access papers (continued):
Sharing a sentence is not in itself a finding about the gene and the disease.
oral squamous cell carcinoma (18 papers, 2013 to 2025). "PD-L1, PD-1, FOXP3, and miR-155 are emerging as key modulators of immune evasion and progression of oral squamous cell carcinoma (OSCC)." (PMID 40806346, 2025). "In this study, we aim to investigate the advantages of four-color mIHC method to detect the expression and localization of CD8, PD-L1, and FOXP3 expression cells in different oral diseases and oral squamous cell carcinoma." (PMID 33364188, 2020). "The aim of this study is to determine the relationship of Foxp3 expression with clinicopathological parameters and prognosis in oral squamous cell carcinoma (OSCC)." (PMID 27457382, 2016). "For example, exosomal circ-0069313 promotes its function by maintaining the level of Foxp3 transferred to Tregs in oral squamous cell carcinoma, and Foxp3 degradation can be inhibited in Tregs via the sponging of miR-325-3p; both of these mechanisms contribute to immune evasion by tumor cells." (PMID 37753074, 2023). "OPMD and oral squamous cell carcinoma (OSCC) tissue sections (N = 270) were analyzed by immunohistochemistry for Treg (CD4, CD25 and FoxP3), Teff (CD8) and immune checkpoint molecules (PD-1 and PD-L1)." (PMID 36009387, 2022). "In oral squamous cell carcinoma (OSCC) cells, CCL20 and FOXP3 mRNA expression is significantly correlated." (PMID 31852159, 2019). "Immunohistochemical staining for CD4, CD8, FoxP3, CD1a, and p16 was performed in 131 oral squamous cell carcinomas from smokers/drinkers and never-smokers/never-drinkers." (PMID 37345025, 2023). "Immunohistochemical method was used to examine the immunoexpression of PD-L1 and number of Foxp3+, CD4+, CD8+ cells in 78 cases of oral squamous cell carcinomas (OSCCs): with better prognosis - OSCCBP (n = 37), and with poorer prognosis - OSCCPP (n = 41), and 18 cases of normal mucosa as a control." (PMID 28669079, 2018).
invasive breast carcinoma (16 papers, 2009 to 2022). A carcinoma that infiltrates the breast parenchyma. "Our t-SNE study of TCGA data from patients with breast invasive cancer reveals that high CCR4 expression in tumor tissue is linked to high FOXP3 expression." (PMID 35222362, 2022). "Bates and co-workers quantified Foxp3+ Tregs in primary ductal carcinoma in situ (DCIS) and invasive breast cancer and found that higher numbers of Foxp3+ Tregs in patients with DCIS correlated with increased risk of relapse." (PMID 19604349, 2009). "In summary, our study indicates that the functional heterogeneity of FOXP3 + TILs represents specific variations in the immunological balance in invasive breast cancer." (PMID 35438346, 2022). "Compared with pure DCIS samples, the degree of CA9+ epithelial cell and FOXP3+ lymphocyte colocalization was significantly higher in the invasive compartment of invasive breast cancer (IDC), but significantly lower in the synchronous DCIS compartment." (PMID 36109587, 2022). "CD4+, CD8 + and FOXP3 + immune cell infiltration was significantly higher in invasive breast cancer compared to pure DCIS (p < 0.001)." (PMID 34952631, 2021). "In our cohort of invasive breast cancer patients, TILs represented the 3.78% on average of the tumor mass, FoxP3+ TILs the 0.55%, and occurred with an equal distribution in the tumor center and margin." (PMID 28885584, 2017). "Of the 100 tumor specimens obtained from primary invasive breast carcinoma, 63 and 57% were evaluated as FOXP3+ tumor cells and as being highly infiltrated by FOXP3+ lymphocytes, respectively." (PMID 24649219, 2013). "These fingerings indicated that FOXP2 and FOXP3 could be a promising biomarker to differentiate Breast Invasive Carcinoma tissues from normal tissues." (PMID 35614183, 2022). "The present study is intended to complement our previous investigations on epithelial-to-mesenchymal transition (EMT) markers and cancer stem cells (CSCs) in normal breast tissue and invasive breast cancer, and on the prognostic significance of Snail and FoxP3 in invasive ductal breast cancer." (PMID 28885584, 2017). "One interesting finding was that some cancers showed a large amount of FoxP3 expression with minor GzmB expression such as lower grade glioma (LGG), invasive breast carcinoma (BRCA) and ovarian serous cystadenocarcinoma (OV)." (PMID 35326588, 2022). "The t-SNE analysis of TCGA data from patients with breast invasive cancer also revealed a strong connection between CCR4 and FOXP3, which was further validated in our laboratory." (PMID 35222362, 2022). "We used immunohistochemistry to quantitate FOXP3, CD4, and CCL20 expression in 156 invasive breast cancers samples." (PMID 31852159, 2019). "We investigated tissue microarrays of 31 invasive breast cancer patients, looking at quantity and topological distribution of CD3+, CD8+, CD20+, Ki67+, FoxP3+ TILs and CD3+/FoxP3+, CD8+/FoxP3+ cell ratios." (PMID 28885584, 2017).
metastatic melanoma (16 papers, 2013 to 2024). A melanoma that has spread from its primary site to another anatomic site. "Hamanishi and collaborators demonstrated that tumor infiltration by CD8+ T lymphocytes was associated with increased FOXP3, regulatory T cells and PD-L1 protein and mRNA in metastatic melanomas." (PMID 26041877, 2015). "Mechanistically, we found that secretomes from human metastatic melanoma cells downregulate CTLA4 mRNA at the post-transcriptional level through miR-155 while upregulating FOXP3 expression in human Treg cells." (PMID 37197667, 2023). "Foxp3 expression was decreased in metastatic melanoma, while CTLA4 expression was significantly increased." (PMID 33669410, 2021). "Based on our current findings generated using anti-FOXP3 antibodies Ab20034 and Ab10563, we conclude that FOXP3 is expressed in 12% of human metastatic melanomas with expression restricted to <1% of cells within these tumors." (PMID 24406338, 2014). "To address this, we performed immunohistochemical staining for FOXP3 on a tissue microarray (TMA) comprising tumors from 146 patients with stage III and stage IV metastatic melanoma, using the rabbit polyclonal anti-FOXP3 antibody Ab10563, directed against the C-terminus of FOXP3." (PMID 24406338, 2014). "Intradermal injection of the mRNAs encoding melan-A, tyrosinase, gp100, MAGE-A1, MAGE-A3, and survivin decreases the frequency of forkhead Box P3+ (Foxp3+)/CD4+ regulatory T cells and Myeloid-derived suppressor cells (MDSCs) in metastatic melanoma patients." (PMID 37834126, 2023). "In this study, we performed a multiplex immunostaining of CD3, FOXP3 and GRZB on both primary and unmatched in-transit metastatic melanoma lesions and defined a novel ratio between different lymphocyte subpopulations, demonstrating its potential prognostic role for cancer immunotherapy." (PMID 34066146, 2021). "In this study, we found that ILT2 could be detected on both CD4+ and CD8+ T cells in patients with metastatic melanoma and that ILT2 correlated with FoxP3 expression." (PMID 24829758, 2014). "Correlations of the prevalence of immune cell subsets with disease outcomes in metastatic melanoma patients after anti-PD-1 therapy have been consistently reported for CD8+ T cells and found in some studies for other immune cell markers, including CD45RO and FOXP3, PD-1, PD-L1, and CD103." (PMID 39766316, 2024).
acute myeloid leukemia (15 papers, 2016 to 2025). Acute myeloid leukemia (AML) is a group of neoplasms arising from precursor cells committed to the myeloid cell-line differentiation. "Intratumoral accumulation of CD4+CD25+Foxp3+ regulatory T (Treg) cells occurs in acute myeloid leukemia (AML), but little is known about the role of tumor cells themselves in this process." (PMID 32849603, 2020). "Related research demonstrated that Treg cells were significantly increased in acute myeloid leukemia (AML), and downregulating the level of CD25+FOXP3+Treg cells in the TME contributed to clinical benefit in patients with refractory AML." (PMID 33986819, 2021). "CD4+CD25+Foxp3+ regulatory T cells (Tregs) accumulate in bone marrow microenvironment in acute myeloid leukemia (AML)." (PMID 30319662, 2018). "For example, in breast cancer, acute myeloid leukemia (AML) and lung cancer, the highest TNFR2 expression levels were found on Foxp3+CD25+CD4+ Tregs." (PMID 35681583, 2022). "GNE-781 displayed anti-tumor activity in an acute myeloid leukemia (AML) model and was also shown to decrease Foxp3 transcript levels in a dose-dependent manner." (PMID 33276800, 2020). "This study aimed to determine the frequency of regulatory T cells (Tregs) (CD4+/FOXP3+) and indoleamine 2,3-dioxygenase (IDO) expression in patients with acute myeloid leukemia (AML)." (PMID 39695001, 2024). "While mutations in DNMT3A act as negative prognostic factor in patients with acute myeloid leukemia (AML), DNTM1 ablation in Teffs and its inhibition by DNMTs inhibitor 5-aza-2′-deoxycytidine (Aza) lead to an increase in Foxp3 expression in these cells." (PMID 34281195, 2021).
celiac disease (15 papers, 2011 to 2026). An autoimmune genetic disorder with an unknown pattern of inheritance that primarily affects the digestive tract. "Increased levels of CD4+CD25+Foxp3+ cells in the circulation and mucosa are associated with active celiac disease." (PMID 21949691, 2011). "Additionally, AD is associated with an increase in FOXP3+ Tregs, whereas celiac disease is associated with a decrease in FOXP3+ Tregs." (PMID 38256267, 2024). "However, a significant benefit was found for hookworm treatment of patients with Coeliac disease, many of whom regained gluten tolerance, accompanied by a significant increase in FOXP3+ Tregs among the intraepithelial lymphocytes, although not in peripheral blood." (PMID 32153025, 2020). "Also, the staining reactions were strong in dual-colour indirect immunofluorescence staining of CD3+CD8− IELs and in an immunohistochemical panel (CD4, CD8, CD19, CD163, and FOXP3) consisting of markers known to be relevant for the pathogenesis of coeliac disease." (PMID 31730447, 2019). "Regulatory T cells (Tregs) also have a role in celiac disease, with recent studies showing increased numbers of circulating and mucosal CD4+Foxp3+ cells in individuals with active celiac disease, as compared to those on a gluten-free diet." (PMID 21949691, 2011). "IL-17A, IFN-γ and Foxp3 mRNA levels correlate in small intestinal mucosa of patients with untreated celiac disease (Untreated CD) but not in symptom-free celiac disease patients on gluten-free diet (Treated CD)." (PMID 23326425, 2013). "In this study, the authors have shown that butyrate coupled with IFN-γ dictates the balance between FOXP3 isoforms, FOXP3 ∆2 and full-length FOXP3, in the intestine of non-celiac controls, contrary to what happens in celiac disease patients, in whom lactate increases both isoforms." (PMID 38396767, 2024). "For instance, whereas the number of Foxp3+ Treg seems to be reduced in the peripheral blood of patients with IBD, the absolute Treg number seems to be increased in the mucosa of patients with IBD or celiac disease, probably as a consequence of the ongoing inflammation." (PMID 22849659, 2012).
esophageal squamous cell carcinoma (15 papers, 2016 to 2025). Esophageal squamous cell carcinoma (ESCC) is a type of esophageal carcinoma (EC) that can affect any part of the esophagus, but is usually located in the upper or middle third. "Cox-regressive analysis indicated that the T stage, N stage, and level of FOXP3 expression were independent prognostic risk factors in esophageal SCC." (PMID 36235242, 2022). "In esophageal squamous cell carcinoma, a correlation has been observed between increased levels of IL‐33 and increased density of FOXP3+ Tregs, which are thought to enhance immune escape." (PMID 40860436, 2025). "Correlation between CD4+CD25+FOXP3+ Tregs, CD8+TILs/CD4+CD25+FOXP3+ Tregs ratio, and clinicopathological characteristics in patients with esophageal squamous cell carcinoma (n = 126)." (PMID 39264227, 2024). "Therefore, the research suggests that a high level of FOXP3 is a poor prognosis factor in esophageal SCC." (PMID 36235242, 2022). "We investigated the density, distribution and relationship of five immune markers CD4, CD8, Foxp3, IL-10 and IgG4 with multiple immunostaining method in 118 esophageal squamous cell carcinoma (ESCC) together with clinical data." (PMID 36891293, 2023). "In another study, the expressions of CD8+, CD4+, FOXP3+, Immunoglobulin G4 (IgG4), and IL-10 and clinical information of 118 patients with esophageal squamous cell carcinoma (ESCC) were assessed with hematoxylin and eosin (H&E), immunohistochemistry (IHC) staining and multi-color Immunofluorescence." (PMID 38077386, 2023). "Periplocin can also induce the death of esophageal squamous cell carcinoma (ESCC) cells in vivo and in vitro by downregulating Foxp3, increasing the expression of DR4/DR5, and increasing the cells' sensitivity to trial." (PMID 35847371, 2022). "Using tissue microarrays of 396 patients who underwent surgery for oesophageal squamous cell carcinoma (ESCC), infiltrated T-cell subsets (CD3, CD8, and Foxp3) and checkpoint protein expression were scored." (PMID 31882943, 2019).
Graves disease (15 papers, 2016 to 2025). Graves' disease is an autoimmune disorder that leads to overactivity of the thyroid gland (hyperthyroidism).It is caused by an abnormal immune system response that causes the thyroid gland to produce too much thyroid hormones. "Main characteristics of included studies on the association between Foxp3 polymorphisms and risk of Graves' disease." (PMID 32612577, 2020). "The absolute number of CD4/CD25/FOXP3 was lower in the Graves’ disease group than in Hashimoto’s thyroiditis group." (PMID 41307767, 2025). "FOXP3 and miR-23a-3p were significantly downregulated in patients with Graves’ disease, whereas SIRT1 and RORγt were upregulated." (PMID 37483618, 2023). "Hashimoto’s thyroiditis is similar to Graves’ disease in that reduced FOXP3 expression levels, and defective Treg function are regulated by SIRT1-mediated aberrant FOXP3 acetylation in patients with Hashimoto’s thyroiditis." (PMID 37483618, 2023). "Moreover, reduced values for CD38+ cells with co-expression of Foxp3 and IL-10 were reported in Graves’ disease pediatric patients." (PMID 34681587, 2021). "Here, we found that a more significant role could be attributed to regulatory B cells characterized by Foxp3 and IL-10 expression, as these subpopulations seemed to play the most crucial role in the course of Graves’ disease therapy." (PMID 34681587, 2021). "Another study reported elevated levels of a rare subset of CD38-FoxP3+IL-10+ Bregs and decreased levels of CD38+FoxP3+IL-10+ Bregs in pediatric patients with Graves’ disease." (PMID 40458534, 2025). "miR-210 targets Foxp3 3’UTR to repress its expression and tune the immunosuppressive function of Tregs in Graves’ disease." (PMID 38741041, 2024). "Further studies showed that the aberrant acetylation of FOXP3, which is regulated by miR-23a-3p by targeting SIRT1, mediated the defective Treg function in patients with Graves’ disease." (PMID 37483618, 2023). "Our study is aimed at detecting the expression of SLAM and SAP in patients with Graves' disease (GD) and analyzing the effect of SLAM/SAP on circulating blood CD4+CXCR5+Foxp3+ follicular regulatory T (Tfr) cells." (PMID 33987447, 2021). "Presumably, expansion of CD38- B cells with Foxp3+ and/or IL-10 expression counteracts reduced numbers of CD38+Foxp3+IL-10+ Bregs and is a sign of a compensatory mechanism aimed at the reduction in autoimmune reactions related to Graves’ disease." (PMID 34681587, 2021). "According to our results, the frequency of CD4/CD25/FOXP3, but not CD4+/CD25 + in Graves’ disease was lower than Hashimoto’s thyroiditis." (PMID 41307767, 2025).
Hashimoto thyroiditis (15 papers, 2018 to 2025). An autoimmune disorder caused by the production of autoantibodies against thyroid tissue. "Cases of PTC with concomitant Hashimoto thyroiditis showed scattered FOXP3+ lymphocytes in the lymphocytic infiltrate of Hashimoto thyroiditis indicating the presence of regulatory T lymphocytes (Treg)." (PMID 32606302, 2020). "Hashimoto’s thyroiditis is also characterized by altered composition of both FoxP3+ and Th17 cell compartments." (PMID 29881372, 2018). "Hashimoto’s thyroiditis (HT) pathogenesis is characterized by a dysregulation of immune tolerance, which may be influenced by genetic variations in the FOXP3 gene, a key regulator of T-regulatory cell function." (PMID 40109804, 2025). "Likewise, a lower risk of PTC remission was observed in patients with a lower ratio of CD8+ / FOXP3+ T lymphocytes in chronic lymphocytic thyroiditis." (PMID 38913547, 2024). "Additionally, FoxP3 + lymphocytic infiltration was more frequent in PTCs smaller than 2 cm in diameter, lacking extrathyroidal invasion and associated with chronic lymphocytic thyroiditis." (PMID 37563607, 2023). "Thus far, although some susceptibility loci have been elaborated, including PTPN22, FOXP3, and CD25, the aetiology and pathogenesis of Hashimoto’s thyroiditis remains unclear." (PMID 30384852, 2018). "Previous studies showed that a greater presence of regulatory T lymphocytes (FOXP3+) and double-negative T lymphocytes (T CD3+ CD4− CD8−) was associated with papillary carcinoma compared to Hashimoto's thyroiditis." (PMID 38913547, 2024). "Suppression of T cell responses could play a clinical role in the development and course of Hashimoto’s thyroiditis, even at the stage of full progression of the disease, because the thyroid tissue of HT patients is infiltrated by CD69+ and CD25+, with moderate numbers of Foxp3+ cells." (PMID 37371976, 2023).